TYR (tyrosinase)
Diseases named in the same sentence as TYR in open-access papers (continued):
Sharing a sentence is not in itself a finding about the gene and the disease.
oculocutaneous albinism type 1 (continued). "Mutations of TYR cause oculocutaneous albinism type 1 (OCA1), which is subdivided in tyrosinase-negative OCA1A and OCA1B, which is characterized by mutations that allow residual tyrosinase activity." (PMID 41002986, 2025). "Human tyrosinase (Tyr) is a glycoenzyme that catalyzes the first and rate-limiting step in melanin production, and its gene (TYR) is mutated in many cases of oculocutaneous albinism type 1 (OCA1)." (PMID 34360537, 2021). "A deficiency in tyrosinase production leads to the total or partial absence of melanin, resulting in the Oculocutaneous Albinism Type 1 (OCA1)." (PMID 28476152, 2017).
Obesity (25 papers, 2014 to 2025). Accumulation of substantial excess body fat. "Atherosclerosis is one of the most serious complications associated with obesity, triggered by ROS and additional factors including enzymes such as tyrosinase and 15-lipoxygenase, a mediator of LDL oxidation." (PMID 29385084, 2018). "LRM has various pharmacological properties, including antioxidant, anti-inflammatory, anti-aging, anticancer, immunomodulatory, anti-fatigue, anti-obesity, antidiabetic, antiviral, and tyrosinase inhibitory activity." (PMID 37836464, 2023). "These compounds demonstrate a wide range of pharmacological activities, including antioxidant, anticancer, antihypertensive, antidiabetic, anti-obesity, anti-tyrosinase, antiallergic, and antiglaucoma properties." (PMID 36840285, 2023). "It has various properties, including tyrosinase inhibition, antioxidant, anti-obesity, anti-diabetic, anti-cancer, anti-photoaging, anti-atherosclerosis, and anti-hepatotoxicity activities." (PMID 36286432, 2022). "For this pharmacological validation, a panel of enzymes were chosen whereby α-amylase and α-glucosidase are used for DM type 2, AChE and BChE for AD, tyrosinase and elastase for cutaneous manifestations and pancreatic lipase for obesity." (PMID 35335362, 2022). "Polyphenols, widely distributed in the genus Melastoma plants, possess extensive cellular protective effects such as anti-inflammatory, anti-tyrosinase, and anti-obesity, which makes it a potential anti-inflammatory drug or enzyme inhibitor." (PMID 34206838, 2021). "Polyphenols, the characteristic component of Melastoma plants, have broad cytoprotective effects, such as anti-oxidation, anti-inflammatory, anti-tyrosinase, and anti-obesity, which make it a potential anti-inflammatory drug or enzyme inhibitor." (PMID 34206838, 2021). "It seems as though O-glycosylation can enhance certain types of biological benefits, including anti-HIV, anti-tyrosinase, anti-rotavirus, antistress, anti-obesity, anticholinesterase, antiadipogenic, and antiallergic activities." (PMID 34946519, 2021). "Current research shows that all parts of M. balbisiana possess anti‐tyrosinase, anti‐lipase, and anti‐xanthine oxidase properties, which may be beneficial for the treatment of obesity, skin problems, or gout." (PMID 39479626, 2024). "The fresh pulp was enhanced with pectin, followed by inoculation with Lactobacillus acidophilus, and freeze-dried showed satisfactory cell viability (approximately 7 log CFU/g DW), whereas an antidiabetic, anti-tyrosinase and anti-obesity potential of the powder was suggested." (PMID 36840102, 2023). "The enzyme inhibitory property of the essential oils was evaluated on enzymes related with neurodegenerative ailments (acetylcholinesterase (ACh) and butyrylcholinesterase (BCh)), diabetes and obesity (α-glucosidase and α-amylase) and skin hyperpigmentation tyrosinase (Tyr) enzymes." (PMID 36770673, 2023). "The extracts were also evaluated for in vitro antioxidant capacity, by complementary assays, and for enzymatic inhibitory properties toward enzymes related with the onset of AD (AChE and BuChE), T2DM (α-glucosidase), obesity/acne (lipase), and skin hyperpigmentation/food oxidation (tyrosinase)." (PMID 36903857, 2023). "Moreover, significant anti-tyrosinase, antidiabetic and anti-obesity potential of the powder was suggested when compared with the effect of the drugs used in current medical practice." (PMID 36840102, 2023). "Phlorofucofuroeckol-A is reported to be present in various brown algae and is a phlorotannin with various biological activities, including tyrosinase inhibition and antioxidant, anti-obesity, anti-diabetic, anti-inflammatory, anti-atherosclerotic, anti-hepatotoxic activities." (PMID 36286432, 2022). "Tyrosinase inhibition impacts profitably upon hypertension, type 2 diabetes and obesity." (PMID 35326885, 2022).
Obesity (continued). "The extract was investigated as a neuroprotective inhibitor of central nervous system (CNS) enzymes such as monoamine oxidase A, tyrosinase, acetylcholinesterase, and as a natural enzyme inhibitor of α-glucosidase and lipase involved in some metabolic disorders such as obesity or type 2 diabetes." (PMID 32668697, 2020).
skin cancer (25 papers, 2012 to 2025). "Tyrosinase is an enzyme involved in melanin biosynthesis and tyrosinase activity abnormalities are associated with skin pigmentation diseases and even skin cancer." (PMID 35458103, 2022). "For the TYR locus, we found significant associations for eye color, skin pigmentation and skin cancer (in GRM5 and TYR)." (PMID 32843070, 2020). "BNC2, HERC2, OCA2, RALY, and TYR are pleiotropic for Category B Phenotypes (skin colour phenotypes) and Category C Phenotypes (skin cancer phenotypes)." (PMID 35907981, 2022). "In the present work, we evaluated the binding affinity, selectivity, and structural stability of KA derivatives complexed with tyrosinase, to investigate their structures as potential competitive inhibitors of the melanogenesis in skin cancer." (PMID 34066283, 2021). "Concerning skin cancer, ATX has been shown to decrease tyrosinase activity on human dermal fibroblasts, which can lead to a malignant transformation of normal melanocytes and promote skin cancer." (PMID 34677429, 2021). "Tyrosinase (EC 1.14.18.1) is an enzyme involved in melanin production, and tyrosinase inhibitors may be clinically useful for the treatment of skin cancer." (PMID 36771597, 2023). "The dysregulation of tyrosinase is involved in skin cancer initiation." (PMID 34066283, 2021). "Our data indicate that PRP4 may decrease the production of melanin in B16F10 cells by downregulating AC–cAMP–MITF–tyrosinase signaling pathway, which subsequently leads to the promotion of skin cancer." (PMID 34209674, 2021). "Regarding skin cancer, the chemopreventive role of ATX (200 μg/kg) was demonstrated in a rat model of UV-DMBA-induced skin tumorigenesis through inhibition of tyrosinase activity and modulation of oxidative stress." (PMID 34677429, 2021). "By controlling pigmentation genes (e.g., TYR, TYRP1, and TYRP2), MITF is the main modulator of melanogenesis in response to environmental stimuli and was also proposed to exert an oncogenic role in several skin cancers." (PMID 32438927, 2020).
Alzheimer disease (24 papers, 2018 to 2025). A progressive, neurodegenerative disease characterized by loss of function and death of nerve cells in several areas of the brain leading to loss of cognitive function such as memory and language. "Recent studies have linked tyrosinase activity not only to age-related skin changes such as spots, photodamage, and pigmentation but also to the development of Alzheimer’s disease." (PMID 39204630, 2024). "Given the considerable side effects associated with current Alzheimer’s treatments, targeting tyrosinase inhibition could represent a dual-purpose therapeutic approach, addressing both skin aging and the progression of Alzheimer’s disease." (PMID 39204630, 2024). "Additionally, it occurred a potential role in the suppression of Alzheimer’s disease risk factors through its antioxidant (metal chelation, radical scavenging capability), anti-tyrosinase and anti-inflammatory characteristics." (PMID 37400624, 2023). "Taking advantage of the two‐photon characteristics of the DST probe, the levels of TYR and ATP were assessed in various brain regions of an Alzheimer's disease (AD) mouse brain model." (PMID 40129186, 2025). "Recent research links tyrosinase not only to age spots, photodamage, and skin pigmentation but also to the pathogenesis of Alzheimer’s disease—an irreversible neurological disorder characterized by cognitive decline, memory loss, and behavioral changes." (PMID 39204651, 2024). "The tyrosinase inhibitory activity of kuwanon G (KG) is unclear, but it has displayed antioxidant, antibacterial, cosmetic, anti-Alzheimer’s disease, anti-inflammatory, and anti-asthmatic properties." (PMID 29891812, 2018). "are reported to exhibit anti-Alzheimer’s disease, anti-inflammatory, fungicidal, anti-cancer, anti-bacterial, and anti-tyrosinase properties." (PMID 29891812, 2018). "Additionally, the two‐photon nature of this probe allows alterations in the TYR and ATP levels to be monitored across different brain regions in an Alzheimer's disease (AD) mouse model." (PMID 40129186, 2025). "Given the significant side effects of current Alzheimer’s treatments, targeting tyrosinase inhibition might offer a dual therapeutic strategy not only for skin aging but also for slowing the progression of Alzheimer’s disease." (PMID 39204651, 2024). "Finally, compound 3, known as α-Cyano-4-hydroxycinnamic acid (α-CCA), has been recognised for its anti-tyrosinase activity and its impact on aldose reductase, suggesting potential benefits for Alzheimer’s disease." (PMID 39065787, 2024). "Tyrosinase is inextricably related to the development of Alzheimer’s disease." (PMID 37297482, 2023). "The RT extract reduces juglone-induced oxidative stress in worms and increases the lifespan and prevents paralysis of C. elegans CL4176, a model of Alzheimer’s disease; the extract is also able to inhibit enzymes such as acetylcholinesterase, monoamine oxidase A and tyrosinase in vitro." (PMID 34069854, 2021). "Thus, inhibition of tyrosinase can control and treat Alzheimer’s disease." (PMID 37400624, 2023). "It is believed that α-glucosidase, acetylcholinesterase (AChE), and tyrosinase are important metabolic enzymes relating with oxidative stress, and they are shown to be the key targets of T2DM, Alzheimer’s disease (AD), mammalian melanogenesis, and fruit or vegetable enzymatic browning, respectively." (PMID 33546380, 2021).
metastatic melanoma (23 papers, 2002 to 2025). A melanoma that has spread from its primary site to another anatomic site. "Indeed, SCD5 re-established the sensitivity to all-trans retinoic acid in A375M metastatic melanoma, associated with increased levels of Tyrosinase, melanin production and reduced proliferation." (PMID 29484133, 2018). "Among them, CD8A, SOX2, TYR, CXCL10 and ICAM1 had the most interaction with other proteins associated with metastatic melanoma." (PMID 39820173, 2025). "Tyrosinase is highly expressed in junctional nevi and metastatic melanoma but decreases with dermal content in benign lesions." (PMID 40509563, 2025). "Intranodal administration of antigen plasmids (pMEL-TYR) and peptides (E-MEL and E-TYR) against Melan A Tyrosinase in patients with metastatic melanoma yielded an overall immune response rate of 50%." (PMID 39211044, 2024). "Since both ANISA and VA are inhibitors of tyrosinase, a melanocyte enzyme, the expression of which increases during tumorigenesis, anticancer potential of the conjugates was tested in several metastatic melanoma cell lines." (PMID 34445104, 2021). "The lack of pigmentation in amelanotic or metastatic melanomas has been suggested as the cause for the inability to detect TYR RNA." (PMID 34422947, 2021). "In vitro treatment with IGFBP-3 of human and murine metastatic melanoma cell lines specifically inhibited the cells' migratory and invasive behaviour, inducing up-regulation of melanocytic differentiation markers such as tyrosinase activity and melanin content." (PMID 24905466, 2014). "Lesions were also immunostained for Melan A, HMB45 and Tyrosinase but no positive cells were detected ruling out a possible combination between atypical metastatic melanoma cells accompanied by dense plasma cell-rich lymphoid infiltrates." (PMID 25996609, 2015). "This transgenic mouse was recently developed in our laboratory using the HLA-A2 restricted high-affinity TCR reactive to human tyrosinase-derived peptide, YMDGTMSQV, isolated from class I-restricted CD4+ T cells from tumor infiltrating lymphocytes of a patient with metastatic melanoma." (PMID 24586745, 2014).
skin aging (19 papers, 2013 to 2025). The gradual irreversible changes in structure of skin that occur as a result of the passage of time.. "This combination results in potent inhibition of enzymes like tyrosinase and elastase, which are associated with skin aging and pigmentation." (PMID 40658325, 2025). "Since melanin overproduction is associated with skin aging and hyperpigmentation, targeting tyrosinase is a common strategy in skin-whitening and anti-aging formulations." (PMID 40872202, 2025). "Accordingly, this study also aims to investigate this potential by examining the extract’s inhibitory effects on enzymes associated with skin aging, specifically elastase, tyrosinase, and hyaluronidase." (PMID 38592804, 2024). "The water extract and EO of P. cubeba were investigated for their in vitro inhibitory activity against elastase and tyrosinase enzymes, associated with skin aging." (PMID 38835963, 2024). "ECM degradation is directly linked to skin aging and is responsible for the increase in activity of certain enzymes such as collagenase, elastase, and tyrosinase that are involved in skin aging." (PMID 33809166, 2021). "Molecular docking and molecular dynamics studies were adopted to estimate and confirm the binding affinity of several compounds and explain their binding pattern at the binding sites of four target enzymes associated with skin aging, namely collagenase, elastase, tyrosinase, and hyaluronidase." (PMID 37746045, 2023). "Overproduction of melanin cause hyperpigmentation, which is a major symptom of skin aging and can be increased by many factors as disturbances in hormonal level, UV radiation and chemicals, therefore tyrosinase inhibitors can enhance skin appearance and lightening." (PMID 37746045, 2023). "Furthermore, this flower extract could inhibit the tyrosinase activity that causes hyperpigmentation, which induces skin aging." (PMID 27912751, 2016). "In order to determine the antiaging effect of Rubus caesius extracts on skin, two enzymes connected with some of the first signs of skin aging: tyrosinase and collagenase, were tested." (PMID 41182101, 2025). "CV extracts also inhibit enzymes like elastase and tyrosinase, indicating their potential in combating skin aging and inflammation." (PMID 41170182, 2025). "In this study, we prepared various extracts from the pitcher, stem, and leaf of Nepenthes miranda using 100% ethanol and assessed their inhibitory effects on key enzymes related to skin aging, including elastase, tyrosinase, and hyaluronidase." (PMID 38592804, 2024). "The aqueous extract displayed substantial in vitro antioxidant activity and appreciable inhibitory activity against the four crucial enzymes (collagenase, elastase, tyrosinase, and hyaluronidase) involved in skin aging." (PMID 36770704, 2023). "Docking the major compounds identified in the extract into the four main protein targets involved in skin aging revealed an appreciable inhibitory potential of these compounds against tyrosinase, elastase, hyaluronidase, and collagenase enzymes." (PMID 38250734, 2023). "The kojic acid (KA) is iron chelator employed in treatment of skin aging, and inhibits tyrosinase, promotes depigmentation." (PMID 24369010, 2013). "A relevant example due to its high market demand is the antiaging potential of the cork extracts: several compounds found in cork extracts have demonstrated the ability to inhibit enzymes such as collagenase, elastase, hyaluronase and tyrosinase, all of which play a key role in skin aging." (PMID 37110699, 2023). "Moreover, the increased production of melanin is another major indication for skin aging and is organized by the enzyme tyrosinase." (PMID 37746045, 2023). "Here, our study investigated the antioxidant, anti-elastase, and anti-tyrosinase properties of plant extracts from 16 Thai plant species and revealed promising natural compounds for the potential development of novel treatments against skin aging." (PMID 36616194, 2022).
skin aging (continued). "Moreover, the flower extract also inhibited collagenase, MMP-2 and tyrosinase activity, all of which are involved in skin aging." (PMID 27912751, 2016). "Therefore, scavenging ROS and inhibiting elastase and tyrosinase activities could be useful in the treatment or even prevention of skin aging." (PMID 36616194, 2022). "TF AR downregulated not only target gene TYR through triggering TF MITF to promote melanin synthesis, but also target gene CDH1, which was modified by phosphorylation, to promote cell-cycle, apoptosis and DNA damage in both middle-aged and elderly skin aging." (PMID 34073305, 2021).
cutaneous melanoma (17 papers, 1995 to 2024). A primary melanoma arising from atypical melanocytes in the skin. "ASIP and TYR pigmentation variants are also associated with cutaneous melanoma and basal cell carcinoma." (PMID 22759494, 2012). "The electrochemical device is capable of detecting the expression of tyrosinase, which is a cancer biomarker involved in the synthesis of melanin, and high levels are found in cutaneous melanoma." (PMID 39355726, 2024). "The proposed platform, integrating MN-based in situ sensing, SERS technology, and TYR responsiveness, holds significant importance for diagnosing cutaneous melanoma." (PMID 38667195, 2024). "In Tsao’s meta-analysis, tyrosinase messenger RNA was positive in 18% patients with stage I cutaneous melanoma disease, 28% with stage II disease, 30% with stage III disease, and 45% with stage IV disease." (PMID 23806209, 2013). "Another nonsynonymous SNP in TYR (R402Q), 106 kb away, is classified as deleterious, has a frequency of 21% in CEU and is associated with mild ocular albinism and risk for cutaneous melanoma and basal cell carcinoma." (PMID 21901107, 2011). "Studies with formalin-fixed, paraffin-embedded sections of cutaneous melanoma showed positive results for melan-A and tyrosinase in 97% and 90% of the cases, respectively." (PMID 17445277, 2007). "Therefore, nuciferine is a potent natural tyrosinase inhibitor and shows promising potential for application in the treatment of hyperpigmentation and skin melanoma." (PMID 37813639, 2023). "Moreover, intracellular tyrosinase inhibition and cytotoxicity on skin melanoma cells (B16) were evaluated." (PMID 35164116, 2022). "Indeed, the phenolic compounds, that transmit the membrane barrier, were evaluated against tyrosinase and elastase enzymes, and also for their intracellular tyrosinase and cytotoxicity activities on skin melanoma cells (B16)." (PMID 35164116, 2022). "The purpose of this study was to evaluate whether tyrosinase mRNA is detectable in the peripheral blood of patients with uveal and cutaneous melanoma and in patients with uveal melanoma undergoing surgical procedures on the eye harbouring the tumour." (PMID 7599046, 1995). "Investigating 448 cutaneous melanomas from the TCGA PanCancer Atlas, we discovered a positive correlation between high ATP1A1 mRNA expression and markers of differentiation and pigmentation (MITF, SOX10, TYR, MLANA)." (PMID 38178183, 2024). "As control, we interrogated Skin Cutaneous Melanoma (SKCM) data to evaluate the correlation data of MITF not only with ZFR, but also with its well-known target gene, namely Tyrosinase (TYR)." (PMID 38472212, 2024).